CD4 (CD4 molecule)
Diseases named in the same sentence as CD4 in open-access papers (continued):
Sharing a sentence is not in itself a finding about the gene and the disease.
lymphopenia (continued). "We interpret the association of CD4 lymphopenia with both CD4+ and CD8+ T-cell turnover as an indirect effect of immune activation rather than homeostasis, as CD4 lymphopenia affected both pools, whereas CD8 lymphopenia affected neither (data not shown)." (PMID 24803534, 2014). "A high incidence of candidiasis diagnosis might be due to the lack of complete immune reconstitution and persistent CD4+ lymphopenia due to therapy failure." (PMID 23510319, 2013). "Models of partial lymphopenia have not been studied and thus it is unclear whether the reduced number of CD4 and CD8 T cells in IL-7Rα449F mice contribute to the increased severity of the influenza A infection in these mice." (PMID 23189186, 2012). "In fact, immature/transitional B cells were also observed in patients with non-HIV-1-related idiopathic CD4+ lymphopenia suggesting that HIV-1-induced CD4+ lymphopenia (and not HIV-1 viremia itself) drives the expansion of these elements in HIV-1-infected patients." (PMID 22474482, 2012). "In clinical observations, patients with higher baseline CD4+ counts exhibited improved immune recovery following Esmolol treatment, while those with severe lymphopenia showed no clear benefit, suggesting that the efficacy of β1AR blockade may vary based on pre-existing immune function." (PMID 40421209, 2025). "IL-7 is known to drive the homeostatic expansion of human naive CD4+ T cells during early life lymphopenia, which led us to examine whether differences in IL-7 receptor (IL-7R) signaling might contribute to the preferential expansion of prenatal naive PLZF+CD4+ T cells." (PMID 37856221, 2023). "Therefore, even though the HPV distribution may not differ in the presence of HIV, CD4+ T cell lymphopenia may facilitate HR-HPV infection due to a lack of effective signaling to enable a robust cytotoxic response." (PMID 36960048, 2023). "Lymphopenia is commonly observed in FIV-infected cats due to an FIV-induced cytopathic impact from a direct replication in CD4+ lymphocytes, but we may not have observed lymphopenia since it is more frequently seen in younger animals, during chronic infection, and in clinically ill cats." (PMID 37112803, 2023). "Similarly, our pharmacological interference with T cell receptor signaling via the calcineurin inhibitor FK506 led to CD4+ T cell lymphopenia with and without EBV infection and compromised immune control of EBV titers as well as associated lymphoproliferative diseases." (PMID 32251475, 2020). "However, IFNγ expression was significantly increased in PTPN22 KO CD4 T cells indicating that PTPN22 influences the inflammatory potential of T helper cells and the difference between WT and KO was particularly pronounced in T cells of mice that underwent lymphopenia induced proliferation." (PMID 32047502, 2020). "Contrary to our initial speculation, pregnancy does not appear to exacerbate the CD4+ T‐cell lymphopenia of HIV infection, and therefore, simple immunophenotyping, such as that undertaken in this study, cannot easily explain the high levels of infection and mortality among pregnant women in SSA." (PMID 28382737, 2017). "We may rule out a role for CD4 T-cell proliferation as a result of CD4 lymphopenia." (PMID 27746782, 2016). "It remains to be determined whether increased granzyme B in CD8+ T cells may be responsible for killing of autologous lymphocyte CD4+ T cells and/or B cells, therefore, contributing further to CD4 and B cell lymphopenia, which is feature of Good syndrome without leukemia." (PMID 26429871, 2015). "Although the vast majority of Vδ2 lymphocytes do not express CD4, in the setting of lymphopenia, rapid T-cell turnover, or heightened immune activation, increased IL-2 levels could lead to CD4 upregulation in Vδ2 cells, making them susceptible to HIV infection in vivo." (PMID 26473478, 2015).
lymphopenia (continued). "However, chronic stimulation of this pathway in the setting of lymphopenia and uncontrolled HIV viral replication could be detrimental for CD4 T cell homeostasis and may contribute to the aberrant immune activation and eventual CD4 T cell depletion observed in these patients." (PMID 24603698, 2014). "Idiopathic CD4 lymphocytopenia (ICL) is a rare and underrecognized immunodeficiency characterized by persistent CD4+ T-cell depletion in the absence of HIV infection or other identifiable causes." (PMID 42028536, 2026). "Of note, following the transplant, the average nucleotide to amino acid sequence ratio also increased significantly for non-XDRTCCs among CD4 and CD8 subsets, consistent with antigen-driven expansion of both sets of clones during post-transplant lymphopenia." (PMID 40313748, 2025). "While CD4+ and CD8+ lymphopenia has been documented in patients with sarcoidosis, it is not a universal clinical hallmark of sarcoidosis." (PMID 41376646, 2025). "When looking at both CD4+ and CD8+ T cell populations, at six months after infection, we noticed that convalescent patients did not display lymphopenia, with full recovery of CD4+ T cells." (PMID 36997530, 2023). "The deletion of miR-150 did not alter the impaired homing of naïve CD4+ cells and DKO mice demonstrated severe peripheral CD4+ cell lymphopenia, as did Rap1KO mice." (PMID 39132043, 2023). "Although there were significant differences of CD4+ lymphocytes in the blood between cART and placebo-treated FIV+ cats, no lymphopenia was appreciated." (PMID 37112803, 2023). "Unlike peripheral CD4 TL, peripheral CD8 T lymphopenia did not appear to be related to patients’ survival." (PMID 35546670, 2022). "We observed that naïve and virtual memory CD8+ T cells, but not CD4+ T cells, were activated in an antigen-independent manner and accumulated in the BM early after CLP, whereas lymphopenia was evident in the spleen." (PMID 36148245, 2022). "The lymphopenia observed in moderate/severe cases was reflected in a significant decrease in the frequency of CD3+ T cells, both in the CD4+ and CD8+ T cell subpopulations, while no changes were observed in monocytes or NKT cells." (PMID 34987646, 2022). "In this study, we found that the lymphopenia in severe patients was mainly in CD8+, but not CD4+ T cell compartment." (PMID 33603759, 2021). "More than one year after the last dose of obinutuzumab/bendamustine, our patient had persistent and pronounced lymphopenia, hypogammaglobulinemia (IgG~200 mg/dL), and no CD20/low CD4 T-cells in peripheral blood by flow cytometry." (PMID 34201591, 2021). "Besides, a study showed that severe infection by SARS-CoV-2 could create lymphopenia with decreased CD4+ and CD8+, but interestingly, there is no decrease in lymphocytes B. In summary, there is an increase in cytokines IL6, IL2R, IL10, TNFα, and MCP-2 production and a decrease in IFN-γ production." (PMID 34078305, 2021). "Relative CD4 and CD8 T cells lymphopenia (with no available absolute count) of 5.6% and 21.1%, respectively, were already present in 2016 (before the diagnosis of sarcoidosis and without steroids)." (PMID 34589827, 2020). "In our study, the development of lymphopenia in severe patients was mainly related to the significantly decreased absolute counts of T cells, especially CD3+, CD4+, and CD8+T cells, but not to B cells or NK cells." (PMID 32633729, 2020). "Such correlations between CD4 and DNT proportion and absolute counts were maintained in patients with ALPS without CD4 lymphopenia (Pearson r: −0.74, p = 0.002, and 0.76, p = 0.0008, respectively) but were absent in patients with ALPS with CD4 lymphopenia." (PMID 31191551, 2019). "Our 29 patients cross-sectional study confirmed a decrease in the absolute numbers but not in the percentages of CD4+ and CD8+ T cells, B, and NK cells, consistent with the lymphopenia described in DMF-treated patients." (PMID 29896193, 2018).
lymphopenia (continued). "Severe lymphopenia was never present, and at PML diagnosis, CD4 and CD8 T-cell counts were 454 mm-3 and 277 mm-3." (PMID 28348775, 2016). "One study of the immune compartments influenced by PCV2 infection demonstrated a lymphopenia involving naïve CD4+CD8- Th cells, memory/effector CD4+CD8+ Th cells and CD4-CD8+ CTLs in diseased, but not healthy animals." (PMID 20028550, 2009). "Additionally, young Ripk1ΔCD4Casp8ΔCD4 mice showed no lymphopenia of peripheral CD4+ T cells, confirming our earlier findings that RIPK1 is required for the protection of peripheral CD4+ T cells from apoptosis." (PMID 40307618, 2025). "The administration of specific mAbs to deplete individual T-cell subsets did not impact the non-depleted immune cell populations (CD4+, CD8+, or WC1+ γδ T cells or CD21+ cells), with the observed lymphopenia occurring after this depletion window of −2 dpi to 2 dpi." (PMID 38357545, 2024). "Interestingly, IL-33 signaling was not necessary for lymphopenia-induced proliferation (LIP) in the spleen of syn recipients, as we observed a similar number of ST2fl/fl and ST2WT donor CD4+ T cells." (PMID 35503257, 2022). "Interestingly, both NK cells and other lymphocytes such as T CD4 and T CD8 cells displayed blood lymphopenia, while no altered levels of these cell subsets were observed in the BAL fluid samples." (PMID 28287491, 2017). "The fact that lymphopenia in our patient mainly relies on CD8+ T cells, and not on CD4+ T cells, conversely to the situation in HIV-infected patients, might in part explain this phenomenon." (PMID 24715969, 2013). "Although 3 days of subcutaneous IL-2 resulted in significant lymphopenia, evidence of immune activation was indicated by a significant rise in the percentage of CD56- (NK cells) and CD3/HLA-DR-positive (activated T cells) subsets, without any change in the percentage of CD4 or CD4 T-cell subsets." (PMID 9579834, 1998).
Immunodeficiency (1,120 papers, 2004 to 2026). Failure of the immune system to protect the body adequately from infection, due to the absence or insufficiency of some component process or substance. "This is the first study to propose and validate a dual-biomarker stratification model that combines a surrogate for insulin resistance (the TyG index) with an immunodeficiency marker (CD4 T-cell count) to assess the mortality risk in HIV-associated sepsis." (PMID 41601726, 2026). "We combined targeted Perturb-seq of 1,032 cis-regulatory elements (CREs) overlapping 4,724 variants across 14 immune diseases with genome-wide Perturb-seq of all expressed genes in primary human CD4+ T cells, spanning 4.1 million cells." (PMID 41959477, 2026). "Based on the interpolated CD4+ T cell count, two participants entered the study with immune deficiency, while 13 others crossed this CD4+ T cell cut-off during follow-up." (PMID 40531922, 2025). "HIV-PH occurs in all stages of HIV infection, which is irrelative to the status of immune deficiency and CD4+ T-cell counts." (PMID 40337277, 2025). "Since the onset of the HIV epidemic, assessing CD4+ T-cells has become a routine procedure for evaluating immune deficiency, with flow cytometry established as the gold standard." (PMID 40204692, 2025). "The other case study’s primary outcome measures for adherence were pill counts, reduced and/or undetectable viral load, and CD4 count > 200, 200 or less being an indicator of severe immune deficiency." (PMID 40289039, 2025). "The current study found that the severity of immunodeficiency is a key determinant, with a lower CD4 cell count linked to virologic failure for INSTI-based ARTs at greater odds, a finding corroborated by other studies such as umbrella reviews." (PMID 41332892, 2025). "All HIV patients in our review who developed hypercalcemia had severe immunodeficiency, marked by significantly low CD4 counts, which is a known risk factor for IRIS." (PMID 40284609, 2025). "Among patients with CD4+ counts below 200 cells/μL, the prevalence of candidiasis exceeded 90%, confirming the role of severe immunodeficiency as a major risk factor." (PMID 40428813, 2025). "A CD4/CD8 cut-off value below 0.4 showed the strongest association with immune dysfunction, including NK+ cells." (PMID 40303366, 2025). "In OA, the frequencies of CD4+ T cells and B cells were lower than those in healthy controls, reflecting the immune dysfunction associated with OA55." (PMID 41028161, 2025). "HIV-associated immune dysfunction can also impact host:microbe interactions, in particular because CD4+ T cells play a critical role in the control of commensal and pathobiont species in the gut." (PMID 41550925, 2025). "In our study, both coinfected animals displayed signs of immunodeficiency, with a substantial loss of CD4+ T cells in their blood, lung, and gut prior to SARS-CoV-2 exposure." (PMID 39066335, 2024). "Again, this indicates an immunodeficiency apart from low CD4 count that predisposes to the development of UNRS." (PMID 38920894, 2024). "Studies focusing on CD4+ T cell depletion and its direct impact on immune deficiency in HIV-infected patients mostly used peripheral blood samples." (PMID 39432486, 2024). "CD4+ T cell depletion and dysregulation of T cell homeostasis during disease progression have been suggested as the underlying mechanism of immunodeficiency." (PMID 38400997, 2024). "This study describes clinical features and cellular and molecular mechanisms underlying immune deficiency in seven patients with biallelic germline variants in CD4." (PMID 38557723, 2024). "Regarding the T CD4 lymphocyte count, patients with severe immune deficiency were in the majority, at 89.3% (75/84)." (PMID 38486188, 2024). "HIV infection represents a significant cause of secondary immune deficiency, characterized by a complex immunopathogenesis that progressively damages the immune system, particularly CD4+ T cells." (PMID 39421098, 2024).
Immunodeficiency (continued). "Nadir CD4+ T cells counts can be used as a surrogate of immunodeficiency, and their loss leads to dysregulation of T cell homeostasis." (PMID 38422171, 2024). "Among these individuals, 14 (78%) were immunocompromised, including 3 HIV-positive patients with CD4 counts between 100 and 200/mm3, one organ-transplant recipient, and four with common variable immune deficiency." (PMID 38543862, 2024). "For instance, nutritional risk was significantly correlated with immune dysfunction (CD4+ < 500 cells/μl), NLR and PLR, but significantly negatively correlated with CD4+, CD8+, CD3+, and LYM counts." (PMID 39086487, 2024). "Further evidence supports Pomalidomide’s efficacy in reversing immune dysfunction associated with MM, such as impaired T-cell distribution and reduced peripheral blood CD4 + and CD8 + T-cells, partly due to TGF-β secretion." (PMID 39316338, 2024). "CD4+ T cell counts reflects the degree of immune deficiency among PLWH, a natural decline in CD4+ T cell counts is one of the gold standards for assessing disease progression in PLWH." (PMID 37697423, 2023). "Uncontrolled HIV-1 replication leads to a gradual loss of CD4+ T cells, which ultimately causes immunodeficiency and immunosenescence and drives multi-morbidities." (PMID 36239345, 2023). "Of note, beyond B-cell deficiency, 50% of patients additionally presented with CD4+ T cell counts below 500/μl, further emphasizing the severe immunodeficiency of the trial population." (PMID 37596280, 2023). "The disease caused by HIV is characterized by a progressive decline in CD4+T lymphocytes leading to immunodeficiency." (PMID 37341221, 2023). "CD4+ T-cell cytotoxicity appears to be promoted by primary immune deficiency, particularly CTLA4 deficiency and antagonism." (PMID 37161048, 2023). "In LCK-deficient patients with combined immunodeficiency, low CD4 expression serves as a specific hallmark." (PMID 38112969, 2023). "Compared to subjects with CD4 counts ≥ 500/μL, the mortality risk steeply increased with more profound immunodeficiency." (PMID 38008809, 2023). "Analysis of differentially expressed genes (DEGs) in naive CD4+ T (T3) cells in infected PB versus uninfected PB showed enrichment of DEGs in pathways associated with endocrine and metabolic disease, immune disease, and parasite infection." (PMID 37039643, 2023). "Our findings demonstrated that RIF is associated with inflammatory response and immune disorders, manifested by the production of pro-inflammatory factors and the imbalance of CD4+/CD8+ T cells." (PMID 36629622, 2023). "The CD4/CD8 ratio is another well-studied marker of immune dysfunction in HIV in addition to the absolute CD4 count and has also been implicated in predicting the magnitude of the T-cell immune response after natural SARS-CoV-2 infection." (PMID 38005996, 2023). "Depletion of T lymphocytes is one of the significant causes of immune dysfunction, mainly manifested in the reduction of CD4+ T and CD8+ T, which further affects the immune function of the body." (PMID 37636994, 2023). "In patients with IEI, a decrease in CD4-positive lymphocytes is often closely associated with combined immunodeficiency diseases, especially SCID." (PMID 37155023, 2023). "For the sake of completeness, however, it should be also underlined that some studies proposed low levels of CD4 count and immunodeficiency of PLHIV as protective factors against the inflammatory response to SARS-CoV-2 infection." (PMID 35972980, 2022). "It is unclear if this is driven by HIV or disparities in comorbidities and other confounding factors, or cellular immune deficiencies, as a previous study reported a low current or nadir CD4 being associated with worse outcomes." (PMID 35382844, 2022). "A cutoff of 200 CD4+ T cells/μl is defined as the key threshold to predict immune deficiency as usual." (PMID 36569204, 2022).